TMEM200B (transmembrane protein 200B)
Synonyms: TTMB
Tractability: Antibody: UniProt predicts a signal peptide or a membrane-spanning region.
Gene: Protein-coding gene on chromosome 1 (29,119,429 to 29,123,918, reverse strand). Ensembl gene ENSG00000253304.
Subcellular location: Membrane
Gene Ontology:
Cellular component: membrane
Genetic constraint (gnomAD): Loss-of-function variants: 12 observed, 14.17 expected, observed/expected ratio (o/e) 0.85, 90% interval 0.54 to 1.37. The synonymous counts are far from expectation, so gnomAD's model fits this gene poorly and the ratio says little. Missense variants: 456 observed, 388.84 expected, observed/expected ratio (o/e) 1.17, 90% interval 1.09 to 1.27. Synonymous variants: 234 observed, 180.87 expected, observed/expected ratio (o/e) 1.29, 90% interval 1.16 to 1.44.
Homologues: Orthologues: chimpanzee TMEM200B (100% identical), macaque TMEM200B (99% identical), dog TMEM200B (95% identical), pig TMEM200B (93% identical), rabbit TMEM200B (93% identical), guinea pig TMEM200B (86% identical), rat Tmem200b (85% identical), mouse Tmem200b (84% identical), zebrafish tmem200b (29% identical), tropical clawed frog tmem200b (26% identical), Drosophila melanogaster CG12502 (16% identical), Caenorhabditis elegans R05D7.3 (12% identical). Paralogues in human: TMEM200A (26% identical), TMEM200C (25% identical).
Diseases named in the same sentence as TMEM200B in open-access papers:
TMEM200B is named in the same sentence as 6 diseases in open-access papers, as found by Europe PMC text mining. Sharing a sentence is not in itself a finding about the gene and the disease. The quoted sentences say what the papers report.
Obesity (1 paper, 2022). Accumulation of substantial excess body fat. "In the present study, growth-related genes, GAL, CENPF, and GPC2, obesity-related gene, PEMT, and CYP3A4, P450, TMEM200B genes were found to be associated with BWF." (PMID 35795788, 2022).
TMEM200B also shares sentences with these, for which no sentence is quoted: tumor (11 papers); cancer (6); bladder cancer (1); melanoma (1); urothelial carcinoma (1).